ACBD4 (acyl-CoA binding domain containing 4)
Description:
Binds medium- and long-chain acyl-CoA esters and may function as an intracellular carrier of acyl-CoA esters.
Synonyms: HMFT0700; FLJ13322
Tractability: Small molecule: a structure with a bound ligand is known. PROTAC: its protein half-life has been measured.
Gene: Protein-coding gene on chromosome 17 (45,132,600 to 45,144,181, forward strand). Ensembl gene ENSG00000181513.
Subcellular location (Human Protein Atlas): Nucleoplasm; Vesicles
Pathways (Reactome):
Metabolism: Peroxisomal lipid metabolism
Gene Ontology:
Molecular function: fatty-acyl-CoA binding
Biological process: fatty acid metabolic process
Cellular component: cytoplasm
Genetic constraint (gnomAD): Loss-of-function variants: 41 observed, 48.82 expected, observed/expected ratio (o/e) 0.84, 90% interval 0.65 to 1.09. The upper end of that interval is the gene's LOEUF score, 1.09, which puts it in group 4 of 6, group 1 being the genes least tolerant of losing a copy. Missense variants: 393 observed, 420.87 expected, observed/expected ratio (o/e) 0.93, 90% interval 0.86 to 1.01. Synonymous variants: 162 observed, 164.53 expected, observed/expected ratio (o/e) 0.98, 90% interval 0.87 to 1.12.
Homologues: Orthologues: macaque ACBD4 (95% identical), pig ACBD4 (84% identical), dog ACBD4 (83% identical), rabbit ACBD4 (81% identical), rat Acbd4 (79% identical), guinea pig ACBD4 (69% identical), mouse Acbd4 (65% identical), chimpanzee ACBD4 (58% identical), tropical clawed frog acbd4 (47% identical), zebrafish acbd4 (43% identical), Drosophila melanogaster CG8814 (26% identical), Drosophila melanogaster Acbp2 (10% identical), and 1 more. Paralogues in human: ACBD5 (39% identical), ECI2 (19% identical), DBI (13% identical), ACBD7 (11% identical).
Diseases named in the same sentence as ACBD4 in open-access papers:
ACBD4 is named in the same sentence as 19 diseases in open-access papers, as found by Europe PMC text mining. Sharing a sentence is not in itself a finding about the gene and the disease. The quoted sentences say what the papers report.
HCMV infection (1 paper, 2022). "For example, ER-peroxisome MCS proteins (ACBD5, ACBD4, VAP-A/B) were altered in a virus infection-specific manner, being increased during HCMV infection and decreased during Infl." (PMID 35953480, 2022).
ACBD4 also shares sentences with these, for which no sentence is quoted: cancer (3 papers); breast carcinoma (1); Charcot-Marie-Tooth disease (1); COVID-19 (1); Diarrhea (1); Fundus dystrophy (1); hepatocellular carcinoma (1); Hypertension (1); Immunodeficiency (1); nemaline myopathy (1); nephronophthisis (1); nephrotic syndrome (1); non-syndromic intellectual disability (1); prostate carcinoma (1); rheumatoid arthritis (1); Stroke (1); type 2 diabetes (1); virus infection (1).